GABRP (gamma-aminobutyric acid type A receptor subunit pi)
Description:
Pi subunit of the heteropentameric ligand-gated chloride channel gated by gamma-aminobutyric acid (GABA). GABA-gated chloride channels, also named GABA(A) receptors (GABAAR), consist of five subunits arranged around a central pore and contain GABA active binding site(s) located at the alpha and beta subunit interfaces (By similarity). When activated by GABA, GABAARs selectively allow the flow of chloride anions across the cell membrane down their electrochemical gradient. Pi-containing GABAARs are mostly located in peripheral tissues. In the uterus, pi subunits modulate uterus contraction by altering the sensitivity of GABAARs to pregnanolone. In the lungs, pi-containing GABAARs contribute to pulmonary fluid transport via luminal secretion of chloride (By similarity).
Tractability: Small molecule: an approved drug acts on it; a structure with a bound ligand is known; a high-quality ligand is known; it belongs to a druggable protein family. Antibody: UniProt places it where antibodies can reach, with medium confidence; UniProt predicts a signal peptide or a membrane-spanning region; its Gene Ontology location is reachable by antibodies, with medium confidence.
Gene: Protein-coding gene on chromosome 5 (170,763,350 to 170,814,047, forward strand). Ensembl gene ENSG00000094755.
Subcellular location: Cell membrane; Apical cell membrane
Gene Ontology:
Molecular function: GABA-A receptor activity; GABA-gated chloride ion channel activity; extracellular ligand-gated monoatomic ion channel activity; monoatomic ion channel activity; transmembrane signaling receptor activity
Biological process: chloride transmembrane transport; synaptic transmission, GABAergic; monoatomic ion transmembrane transport; monoatomic ion transport
Cellular component: apical plasma membrane; GABA-A receptor complex; GABA-ergic synapse; plasma membrane; membrane
Genetic constraint (gnomAD): Loss-of-function variants: 43 observed, 41.06 expected, observed/expected ratio (o/e) 1.05, 90% interval 0.82 to 1.35. The upper end of that interval is the gene's LOEUF score, 1.35, which puts it in group 5 of 6, group 1 being the genes least tolerant of losing a copy. Missense variants: 463 observed, 500.21 expected, observed/expected ratio (o/e) 0.93, 90% interval 0.86 to 1. Synonymous variants: 194 observed, 191.82 expected, observed/expected ratio (o/e) 1.01, 90% interval 0.9 to 1.14.
Homologues: Orthologues: chimpanzee GABRP (99% identical), macaque GABRP (99% identical), rabbit GABRP (96% identical), dog GABRP (95% identical), pig GABRP (94% identical), rat Gabrp (93% identical), mouse Gabrp (93% identical), guinea pig GABRP (92% identical), tropical clawed frog gabrp (57% identical). Paralogues in human: GABRB3 (40% identical), GABRD (40% identical), GABRB1 (39% identical), GABRB2 (39% identical), GABRQ (34% identical), GABRR2 (33% identical), GABRR3 (33% identical), GABRR1 (33% identical), GLRA1 (32% identical), GLRA3 (32% identical), GLRA2 (32% identical), GABRA4 (29% identical), and 33 more.
Diseases named in the same sentence as GABRP in open-access papers:
GABRP is named in the same sentence as 41 diseases in open-access papers, as found by Europe PMC text mining. Sharing a sentence is not in itself a finding about the gene and the disease. The quoted sentences say what the papers report.
breast carcinoma (27 papers, 2006 to 2026). "SERPINB5 has been indicated to inhibit tumor progression, DSC3 downregulation has been linked with several cancer types and GABRP over-expression has been linked with poor prognosis, metastatic cancer, basal-like breast cancer." (PMID 39580456, 2024). "GABRP expression levels are an important indicator of the risk of recurrence of breast cancer and mortality." (PMID 34790061, 2021). "When used in combination with mertansine, similar antineoplastic properties were also observed at nanomolar concentrations 71, further underlining the prospective role of GABRP as a therapeutic target in breast cancer." (PMID 34790061, 2021). "In addition, two identified genes, GABRP, positively associated with young breast cancer, and ESR1, down-regulated in young breast cancer, were also included." (PMID 25990390, 2015). "This investigation suggested that GABRP gene expression may be associated with high-grade breast cancer in Hispanic women; although this needs additional study." (PMID 22792365, 2012). "In breast cancer, the GABA‐A receptor pi subunit (GABRP) promotes cellular proliferation and differentiation through the activation of the ERK1/2 signaling pathway, enhancing the invasive potential of tumor cells." (PMID 41583906, 2026). "The overexpression of GABRP has been shown to maintain stem cell characteristics in breast cancer, providing support in chemoresistance and promoting migration." (PMID 37370820, 2023). "In breast cancer, GABRP was found to control the stemness of triple-negative breast cancer cells through epidermal growth factor receptor signaling." (PMID 35967794, 2022). "LINC02188 has been shown to be upregulated in triple-negative breast cancers, while PROM1, ROPN1, GABRP, and FDCSP were previously associated with a cancer stem cell signature in a basal-like breast cancer phenotype." (PMID 33525353, 2021). "In one study, most of the healthy controls (51 out of 53) showed low expression levels of GABRP compared to patients with breast cancer 76, and of the 2 remaining controls that exhibited high GABRP levels, 1 participant was pregnant (first trimester)." (PMID 34790061, 2021). "Elevated levels of GABRP have been previously reported in circulating breast cancer cells 72,73,74 and isolated lymph nodes from patients with breast cancer." (PMID 34790061, 2021). "Previous studies have linked GABRP with KRT5, KRT6B, KRT14, and KRT17 in breast cancer pathogenesis 85, as several cytokeratins have been implicated in cancer cell migration 86,87,88." (PMID 34790061, 2021). "We also developed a potential IHC assay to assess GABRP protein expression in clinical tissues, and found that nearly half of all breast cancers were positive for GABRP, including ER positive cancers." (PMID 31624295, 2019). "We also examined GABRP mRNA expression in breast cancer cell lines in the Cancer Cell Line Encyclopedia (CCLE)." (PMID 31624295, 2019). "The expression of GABA (A) receptor pi (GABRP) plays a role in initiation and progression of basal-like tumors, and has therapeutic potential in basal-like breast cancer." (PMID 31296201, 2019). "We examined GABRP protein levels in five breast cancer cell lines and similar to the mRNA expression data, we found that both TNBC (HCC1143, MDA-MB-468, MDA-MB-231) and non-TNBC (SKBR3 and BT-474) cells express comparable GABRP protein levels." (PMID 31624295, 2019). "Within each breast cancer subtype, GABRP expression was heterogeneous and mainly detected in tumor epithelial cells." (PMID 31624295, 2019). "We analyzed 4467 breast cancers and identified GABRP as top expressed gene in TNBC with low expression in most normal tissues." (PMID 31624295, 2019). "GABRP protein was localized to cell membrane with broad range of receptors/cell and expressed by nearly half of breast cancers tissues." (PMID 31624295, 2019).
breast carcinoma (continued). "We therefore, tested the naked (unconjugated) commercially available ECD-binding GABRP-Ab that suppressed the growth of breast cancer cell lines, particularly MDA-MB-468, in a dose-dependent manner starting at 20 μg/ml." (PMID 31624295, 2019). "Survival analysis was performed to explore the correlation between the 4 DEGs (GFRA3, NPY1R, PTPRN2 and GABRP) with patients’ survival in over 400 breast cancer samples from TCGA database." (PMID 29423105, 2018). "Research showed GABRP stimulates basal-like breast cancer cell/ triple negative subtype migration through activation of extracellular regulated kinase 1/2 (ERK1/2)." (PMID 28245581, 2017). "Our newly identified function and mechanism of GABRP in ovarian cancer cells are consistent with those shown previously in pancreatic and breast cancer cells." (PMID 28524180, 2017). "In comparison with those consistently classified as basal-like (n = 46), the tumors clustered as ERBB2 (n = 12) showed a lower average expression in KRT17, KRT5 and especially GABRP, which has been reported to be associated with ER-/HER2- breast cancers." (PMID 16846532, 2006). "Evidence has showed that the pi subunit of the GABRP is expressed in the basal-like breast cancer (BLBC) subtype and may be associated with the development of breast cancer metastasis." (PMID 40900801, 2025). "Notably, the transcripts occupying the block associated with PAM50 subtype include CA12, GABRP, NAT1 and TBC1D9, which have been previously proposed as predictor genes for breast cancer mortality, recurrence and drug response." (PMID 35758795, 2022). "GABRP is a disseminated tumor cell marker in the metastatic breast cancer field." (PMID 35846884, 2022). "Almost 50% of all breast cancer types exhibit high GABRP expression levels." (PMID 34790061, 2021). "GABRP was also overexpressed in the basal subtype of TCGA breast cancer cohort." (PMID 31624295, 2019). "Interestingly, it has also been reported that GABRP can stimulate basal-like breast cancer cell migration through the activation of ERK1/235." (PMID 29785036, 2018). "Previous study suggested that GABRP is differentially expressed in breast cancer." (PMID 29423105, 2018). "With the progression of breast cancer, GABRP was down-regulated progressively." (PMID 29423105, 2018). "Particularly, GABRP increased (P = 0.005) while ESR1 decreased (P = 0.009) in young breast cancer." (PMID 25990390, 2015). "This indicates that residual over-expression of GABRP, which is unexplained by the negative correlation with these other genes, is associated with reduced risk of breast cancer mortality and recurrence." (PMID 23819905, 2013). "GABRP was reported to be down-regulated in 76% of breast cancers and was progressively down-regulated as tumor growth progressed, suggesting that its role may be as a tumor suppressor." (PMID 23819905, 2013). "Six of the 11 non-mitosis related genes were previously associated with poor survival in breast cancer patients: KRT17, MMP12, SLC7A5, SQLE, GABRP and PA2G4, but the remaining 5 had not been previously associated with cancer risk: CCDC86, NUP107, NUTF2, WASF1 and ELOVL6." (PMID 23077491, 2012). "Interestingly, GABRP positive cases were also found among hormone receptor positive breast cancers." (PMID 31624295, 2019). "We found that the seven GABAA receptor subunits were upregulated in TNBC breast cancers, including GABRA1, GABRA5, GABRD, GABRE, GABRP, GABRQ, and GABRG3." (PMID 36923530, 2023). "GABA-A receptor GABRP is required for maintaining basal-like cytokeratin expression, ERK1/2 phosphorylation and pro-migratory phenotype of breast cancer cells." (PMID 35326596, 2022). "Multivariable analyses using the LASSO revealed that expression of PGR, ESR1, NAT1, GABRP, TBC1D9, SLC39A6 and LRBA of the 32 gene candidates was collectively the most important predictors for both breast cancer mortality and recurrence." (PMID 23819905, 2013).
breast carcinoma (continued). "Furthermore, the community cohesion scores successfully discover the known breast cancer subtypes and we suggest new targeted therapy targets for triple negative breast cancer (e.g. KIT and GABRP)." (PMID 38622359, 2024). "We next examined GABRP protein with IF, and chromogenic IHC of FFPE sections of cell line pellets and tissues of surgically resected primary breast cancers." (PMID 31624295, 2019). "We compared mRNA expression profiles of TNBC with other breast cancer subtypes to identify genes that are overexpressed on TNBC surface, and identified gamma-amino-butyric-acid receptor π subunit (GABRP) as the most promising candidate gene for further functional experiments." (PMID 31624295, 2019). "In our list of candidate targets, some genes including, for example, the gamma-aminobutyric acid receptor subunit pi (GABRP) and cadherin 3, type 1 (CDH3), were characterized by high expression in breast cancer versus normal tissues, but with relatively high levels in normal breast." (PMID 26700623, 2016). "Notably, GABRP and ESR1 previously reported to be related to young breast cancer were included in these differentially expressed genes and validated by qRT-PCR, proving the reliability of our data mining and allocation of samples." (PMID 25990390, 2015). "Most importantly, there are several genes that can distinguish the four breast cancer subtype as specific therapeutic targets for each subtype, including EFCAB2 for luminal A, ATG16L2 for luminal B, C1QTNF6 and NDUFS6 for HER2+, as well as CHERP, TIAM1, and GABRP for TNBC." (PMID 28245581, 2017). "In contrast to clinical datasets, GABRP transcript levels were comparable between most TNBC and non-TNBC breast cancer cell lines." (PMID 31624295, 2019).
pancreatic cancer (10 papers, 2020 to 2025). "Research reveals that GABRP orchestrates tumor microenvironment remodeling in pancreatic cancer by modulating KCNN4-dependent calcium ion flux, a mechanism independent of GABA transmission." (PMID 40901676, 2025). "Adding GABA to cell culture media promoted the proliferation of pancreatic cancer cells expressing GABRP, which is somewhat consistent with our study." (PMID 38263045, 2024). "It was reported that GABRP regulated macrophage recruitment and tumor progression in pancreatic cancer." (PMID 35967794, 2022). "We took advantage of GEO datasets to identify GABRP as a candidate gene that is differentially expressed between gemcitabine-resistant pancreatic cancer and normal cells." (PMID 35846884, 2022). "Functional assays including cell viability, colony formation, invasion, quantitative PCR and western blotting techniques were performed to validate the roles of CD44 and GABRP playing in mediating the gemcitabine resistance in pancreatic cancer cells." (PMID 35846884, 2022). "Both CD44 and GABRP were highly expressed in 178 pancreatic cancer patients which were validated in the starbase database." (PMID 35846884, 2022). "Our current data showed that depletion of CD44s in pancreatic cancer cells rendered them chemoresistant, and a significant reduction in GABRP was observed in CD44s knockdown cells." (PMID 35846884, 2022). "Clinically, GABRP expression was significantly upregulated in the tissues of patients with pancreatic cancer compared to the normal samples, and the overall survival rate of patients with low GABRP expression was longer." (PMID 35846884, 2022). "GABRP has been reported to play an immunomodulatory role in pancreatic cancer in a neurotransmitter independent manner, promoting macrophage infiltration by inducing the expression of CXCL5 and CCL20, and thereby affecting tumor growth and metastasis." (PMID 34957220, 2021). "Our findings suggest that GABRP may serve as a CD44s downstream target to diminish gemcitabine resistance in pancreatic cancer, and both CD44s and GABRP molecules have the potential to become prognostic biomarkers for PDAC patients with gemcitabine resistance." (PMID 35846884, 2022). "CD44 and GABRP co-expression was positively correlated in 178 pancreatic cancer patients." (PMID 35846884, 2022). "We built the first link between GABRP and gemcitabine in pancreatic cancer, and we report, for the first time, that GABRP might be downstream of the CD44 effector gene in gemcitabine-resistant pancreatic cancer cells." (PMID 35846884, 2022). "The expression of both CD44 and GABRP was upregulated in pancreatic gemcitabine resistant cells and tumor tissues compared to the null resistant cells and normal tissues, and they were significantly co-expressed in patients with pancreatic cancer." (PMID 35846884, 2022). "We hypothesized that GABRP is required for CD44 isoforms to induce chemoresistance in pancreatic cancer." (PMID 35846884, 2022). "Because both platforms indicated that the pancreas contained higher levels of GABRP, we took advantage of our pancreatic cancer CFPAC-1 cells to test whether GABRP played an indispensable role in pancreatic cancer progression." (PMID 35846884, 2022). "Targeting CD44 and GABRP may have a synergistic effect on the suppression of gemcitabine-induced resistance in pancreatic cancer." (PMID 35846884, 2022). "Upregulation of GABRP significantly contributed to pancreatic tumor growth and metastasis." (PMID 35846884, 2022). "Moreover, GABRP is the pi subunit of the GABAA receptor and the mechanism of GABRP regulating progression of pancreatic cancer has been discovered." (PMID 33117704, 2020). "GABRP may contribute to CD44-induced gemcitabine resistance in pancreatic cancer." (PMID 35846884, 2022). "Overexpressed pancreatic cancer receptors include SLC2A1, MET, IL1RAP, NPR3, GABRP, SLC6A6, and TMPRSS4." (PMID 35359382, 2022).
pancreatic cancer (continued). "Of note, long term gemcitabine resistant pancreatic cancer cells detected increased expression of CD44 and GABRP." (PMID 35846884, 2022). "The L5 proteins of 3 serotypes of adenovirus HAdV2, HAdV3, and HAdV5 are docked with the seven highly expressed pancreatic cancer receptors SLC2A1, MET, IL1RAP, NPR3, GABRP, SLC6A6, and TMPRSS4." (PMID 35359382, 2022). "We identified 7 highly expressed pancreatic cancer cell surface receptors (MET, NPR3, IL1RAP, SLC2A1, SLC6A6, GABRP, and TMPRSS4) in all the analyzed datasets." (PMID 35359382, 2022). "In addition to protein levels, NSD3 induces global H3K36 dimethylation in pancreatic cancer cells and influences the mRNA levels for genes including ADAM28, ADAM9, BIRC3, CXCL5, DUOX2, GABRP, ITGB6, and RAB11FIP1." (PMID 37062069, 2023). "Likewise, GABA raises extracellular Ca2+ levels and upregulates the MAPK/ERK signaling cascade by elevating GABRP (a subunit of GABAA) expression, resulting in stimulation of pancreatic cancer development." (PMID 35295188, 2022). "We initiated the data mining of Gene Expression Omnibus (GEO) datasets focusing on gemcitabine-resistant versus sensitive cells, and pancreatic cancer verses adjacent non-cancerous tissues, and identified the overlapping gene, gamma-aminobutyric acid type A receptor subunit Pi (GABRP)." (PMID 35846884, 2022). "However, the functional role of GABRP-mediated chemoresistance in any cancer type has not been explored, especially in pancreatic cancer." (PMID 35846884, 2022).
triple-negative breast carcinoma (5 papers, 2021 to 2025). An invasive breast carcinoma which is negative for expression of estrogen receptor (ER), progesterone receptor (PR), and human epidermal growth factor receptor 2 (HER2). "This is consistent with a previous study in which GABRP was recognized as a potent activator of triple negative breast cancer (TNBC)." (PMID 40583063, 2025). "Similarly, GABRP sustains the self-renewal capacity of triple-negative breast cancer stem cells via EGFR pathway activation, while also governing airway epithelial progenitor differentiation by regulating goblet cell formation, thereby maintaining tissue homeostasis." (PMID 40901676, 2025).